AR (androgen receptor)
Diseases named in the same sentence as AR in open-access papers (continued):
Sharing a sentence is not in itself a finding about the gene and the disease.
neuropathy (4 papers, 2010 to 2019). A disorder affecting the nervous system that manifests with pain, tingling, numbness, and/or muscle weakness. "This evidence consists mainly of 2 major findings: that myopathy precedes neuropathy in mice with genetic polyQ expansion mutations in the AR, and also that overexpression of AR in muscle fibers is sufficient to reproduce several hallmark features of KD/SBMA." (PMID 20886071, 2010). "Diabetic complications including neuropathy, nephropathy, cataracts, and retinopathy are considered to result from the accumulation of sorbitol, which is obtained from reduction of glucose by the catalytic activity of aldose reductase (AR, EC 1.1.1.21) in the polyol pathway." (PMID 28326319, 2017).
Onset (4 papers, 2019 to 2025). The age group in which disease manifestations appear. "Spinal and bulbar muscular atrophy (SBMA) is an X-linked, adult-onset neuromuscular disease caused by a CAG repeat expansion within the first exon of the androgen receptor (AR) gene." (PMID 40548375, 2025). "Spinal and bulbar muscular atrophy (SBMA) is an X-linked and adult-onset neuromuscular disease caused by abnormal CAG repeat expansions in the androgen receptor (AR) gene." (PMID 31537808, 2019). "But in AR mutation, 32 (57.1%) biopsy was not performed most likely because of the high risk of percutaneous renal biopsy in patients with congenital-onset SRNS." (PMID 35755072, 2022).
transitional cell carcinoma (4 papers, 2013 to 2024). A malignant neoplasm arising from the transitional epithelium, usually affecting the urinary bladder, ureter, or renal pelvis. "Other reports have indicated that androgen receptor deprivation improved urothelial cell carcinoma recurrence from pathways other than those of ERα and ERβ." (PMID 38357083, 2024). "AR expression was found to be the strongest in the transitional epithelial cells HCV29 and in transitional cell carcinoma T24." (PMID 31119584, 2019). "We found that nonmalignant transitional epithelial cells and transitional cell carcinoma had higher levels of AR expression compared to high-grade or muscle-invasive tumor cell lines." (PMID 31119584, 2019). "A study of transitional cell carcinoma showed that AR is expressed in women patients and found that 30% of the bladder cancer tumors are AR positive and that nontumor tissue may also express AR." (PMID 26347776, 2015).
Urinary incontinence (4 papers, 2017 to 2024). Loss of the ability to control the urinary bladder leading to involuntary urination. "This suggests that TCS's dose-dependent androgen receptor agonism may contribute to enhancing androgen activity in pelvic floor muscles, potentially protecting against urinary incontinence." (PMID 38373965, 2024). "Clinical trials assessing the efficacy of GTx-024 for urinary incontinence (NCT03241342) and AR-positive triple-negative breast cancer (NCT01616758) are complete and release of results was pending at the time this manuscript was written." (PMID 31319382, 2019).
Uterine leiomyoma (4 papers, 2018 to 2026). The presence of a leiomyoma of the uterus. "AR was also found in uterine fibroids, suggesting a potential role for AR in the development of uterine fibroids." (PMID 36358974, 2022). "Furthermore, we clarify the genetic distinction between adenomyosis and uterine leiomyomas, highlighting their divergent responses to androgen receptor signalling." (PMID 41968335, 2026).
adenoid cystic carcinoma (3 papers, 2019 to 2021). A malignant tumor arising from the epithelial cells. "The other study showed AR abundance in about 6.6% cases of salivary gland adenoid cystic carcinoma." (PMID 30382367, 2019). "Importantly﻿, the presence of more frequent special histological subtypes with poor prognosis as medullary carcinoma, ILC and adenoid cystic carcinoma in the AR− versus the AR+ group (42% versus 28%) in our cohort, may have an impact on survival as pointed to by other studies." (PMID 35047068, 2021). "No necrosis, TILs and AR expression were found in adenoid cystic carcinomas; the higher percentage of necrosis was identified in metaplastic carcinoma (83.7%), whereas the highest proportion of TILs was seen in medullary tumors (92.3%)." (PMID 32487046, 2020). "Patients with adenoid cystic carcinoma had an OS of 100% at 10-years follow-up, with prevalently low/intermediate grade, low lymph node ratio, absence of necrosis, lymphocytic infiltrate, and AR expression." (PMID 32487046, 2020).
adenomyosis (3 papers, 2024 to 2026). The growth of endometrial tissue inside the muscular wall of the uterine corpus. "One study investigated the protein expression of AR in adenomyosis lesions compared with eutopic endometrium from 10 patients." (PMID 39935764, 2025). "There is a paucity of data on AR expression in adenomyosis lesions, with only one study of small sample size included." (PMID 39935764, 2025). "Future studies are imperative to define the exact role of AR in adenomyosis lesions comprehensively." (PMID 39935764, 2025). "Human studies were included and identified using a combination of exploded MeSH terms (‘adenomyosis’) and free-text search terms (‘oestrogen receptor’, ‘progesterone receptor’, ‘androgen receptor’, ‘hormone receptor’)." (PMID 39935764, 2025). "There is a notable research gap concerning AR levels in adenomyosis lesions, which is an area for future research given the potential role of AR in endometrial proliferation." (PMID 39935764, 2025). "Investigating the interplay between androgens, AR, and other hormonal factors within the context of adenomyosis will provide valuable insights into the pathogenesis and potential therapeutic targets for this condition." (PMID 39935764, 2025). "Androgen receptor (AR) is present in both ectopic and eutopic endometrium in adenomyosis." (PMID 39935764, 2025). "In the context of adenomyosis, altered AR expression could contribute to the pathogenesis, as AR can interact with both oestrogen and progesterone signalling pathways." (PMID 39935764, 2025). "Priority should be given to studies that simultaneously examine multiple hormone receptors (ER, PR, AR, GnRH-R, GPER) across different menstrual cycle phases and compare the adenomyosis lesions to specific endometrial subregions." (PMID 39935764, 2025). "However, knowledge about the role of AR in adenomyosis is limited due to the lack of published literature." (PMID 39935764, 2025).
airway hyperresponsiveness (3 papers, 2022 to 2025). "Estrogen enhances airway hyperresponsiveness and the production of type 2 cytokines through the estrogen receptor-α, while testosterone reduces the proliferation of innate lymphoid cells 2 and the production of type 2 cytokines via the androgen receptor." (PMID 40605091, 2025).
baldness (3 papers, 2017 to 2026). "The top X chromosome gene-based findings included the androgen receptor (AR), which has been well established as a baldness associated gene, along with its upstream (EDA2R) and downstream (OPHN1) genes." (PMID 28196072, 2017). "Similarly, Ellis and coworkers reported that smoking status had little effect on the estimated OR of the SNP rs6152, one of the first chromosome X polymorphisms near the AR locus that has been linked to baldness." (PMID 39861428, 2025). "Androgen receptor (AR) signaling plays a key role in male pattern baldness." (PMID 41751951, 2026).
bone tumor (3 papers, 2011 to 2019). "Nuclear AR staining in bone metastases associate with poor outcome in patients, suggesting AR signaling in promoting bone tumor growth." (PMID 31638934, 2019). "Our in vivo data with bone tumor models demonstrating that enzalutamide can inhibit bone tumor growth and androgen biosynthetic enzyme expression in tumors, further suggest the effectiveness of anti-AR therapies for metastatic bone tumors." (PMID 31638934, 2019). "In this study, we tested the biological significance of ERG induced androgen production on bone tumor growth and targeting AR signaling with enzalutamide." (PMID 31638934, 2019). "We utilized ERG knockdown approach in TMPRSS2-ERG positive cells and targeting the AR function with enzalutamide for bone tumor growth." (PMID 31638934, 2019). "Human bone tumor biopsy studies show that androgen production is present in bone tumors and activation of AR signaling contributes to bone tumor growth." (PMID 31638934, 2019). "Luciferase tagged VCaP scr and shRNA infected cells were used in an intra-tibial animal model for bone tumor growth analysis and enzalutamide treatment used to inhibit AR signaling in bone tumors." (PMID 31638934, 2019). "Western blotting analyzed VCaP bone tumor samples for ERG, AR, AKR1C3 and HSD3B1 and HSD3B2 expression." (PMID 31638934, 2019). "For example, one study reported that genistein inhibited PC3 bone tumor growth in SCID mice, and another showed that genistein decreased lung metastasis in androgen receptor-negative PC3-M implanted mice, which were fed genistein-enriched chow." (PMID 21603581, 2011). "Our in vitro observations were substantiated in several in vivo models of PCa growth, including an AR-positive castrate-resistant primary human xenografts (MDA PCa 133) that cannot be grown in tissue culture and orthotopic and bone tumors derived from PC-3 cells (AR negative)." (PMID 23300537, 2012).
Cerebral ischemia (3 papers, 2013 to 2024). Restriction of arterial blood supply to the brain associated with insufficient oxygenation to support the metabolic requirements of the tissue. "The androgen receptor (AR) has also been implicated in the response to cerebral ischemia and ischemic preconditioning and may account for some of the observed sex differences in response to IRI." (PMID 39471208, 2024). "None of these studies did whether the relation of testosterone and neurological deficit during the acute phase of cerebral ischemia has been mediated via AR or cerebral aromatase." (PMID 23401794, 2013). "Therefore, to be close to the actual conditions of cerebral ischemia, we assessed the effect of testosterone via androgen receptor and aromatization to estrogen on cerebral ischemia by flutamide and letrozole pretreatment in gonadally intact rats that they subjected to tMCAO." (PMID 23401794, 2013).
cervical intraepithelial neoplasia (3 papers, 2015 to 2024). "Recently, we reported that forkhead box transcription factor P4 (FOXP4) is associated with the androgen/AR pathway in cervical intraepithelial neoplasia cells." (PMID 38890503, 2024). "Immunohistochemistry studies have shown that 100% of AR was expressed in normal epithelium and low grade cervical intraepithelial neoplasia (LSIL-CIN1) (n = 30)." (PMID 35886904, 2022). "However, AR expression was observed only in 63% of high-grade cervical intraepithelial neoplasia (HSIL-C 2/3) (n = 30) and 23% of infiltrating squamous cell carcinoma (ISCC) (n = 13)." (PMID 35886904, 2022). "One study demonstrated the expression of AR by immunohistochemistry in 100% (30/30) of normal epithelium, 100% (30/30) of low-grade cervical intraepithelial neoplasia, and 63% (19/23) of high-grade cervical intraepithelial neoplasia, as well as in 23% (3/13) of invasive squamous cell carcinoma." (PMID 25595907, 2015).
chondrosarcoma (3 papers, 2011 to 2022). A malignant cartilaginous matrix-producing mesenchymal neoplasm arising from the bone and soft tissue. "We investigated the protein expression of estrogen receptor alpha (ESR1), androgen receptor (AR), and aromatase in tumor specimens of various chondrosarcoma subtypes, and (primary) chondrosarcoma cultures." (PMID 22613849, 2011). "As androstenedione is a steroid precursor for estrogens as well as androgens we also investigated the possibility of AR involvement in chondrosarcoma proliferation." (PMID 22613849, 2011). "Only a few strongly AR positive cells were detected in a minority of the chondrosarcomas of various subtypes." (PMID 22613849, 2011). "This suggests no significant role for AR signaling in chondrosarcoma proliferation, which is consistent with the fact that very few tumors express AR." (PMID 22613849, 2011).
colon adenocarcinoma (3 papers, 2006 to 2022). "Out of the 10 cases selected initially as colon adenocarcinoma, one tumor displayed AR immunoreactivity in scattered malignant glands but was negative in the poorly differentiated regions of the tumor." (PMID 17020615, 2006). "The rest of the colon adenocarcinoma cases showed non-reactivity of the nuclei with AR although variable cytoplasmic staining was noted in 7 of the 9 cases." (PMID 17020615, 2006).
congestive heart failure (3 papers, 2012 to 2023). Failure of the heart to pump a sufficient amount of blood to meet the needs of the body tissues, resulting in tissue congestion and edema. "Enzalutamide inhibition of AR activity and signaling may lead to the release of coactivators that can specifically bind to the mutated MR, further increasing the activation of the MR signaling pathway and contributing to the subsequent development of congestive heart failure." (PMID 35740293, 2022).
demyelinating disease (3 papers, 2023 to 2024). A broad group of disorders that affect the myelin sheaths that cover the neurons. "However, the potentially most important therapeutic implication of our results is the indication that astrocytes are a viable target for AR-mediated adjuvant treatment of demyelinating diseases by alleviating the pathologically increased production of at least some pro-inflammatory mediators." (PMID 38534751, 2024).
Duchenne muscular dystrophy (3 papers, 2015 to 2023). Duchenne muscular dystrophy (DMD) is a neuromuscular disease characterized by rapidly progressive muscle weakness and wasting due to degeneration of skeletal, smooth and cardiac muscle. "Another example is the use of AR agonist compounds in the treatment of Duchenne muscular dystrophy (DMD)." (PMID 31766271, 2019). "Although AR is expressed at high levels in muscle, in the reports about corticosteroids for the treatment of Duchenne muscular dystrophy (DMD), this was not mentioned and the authors reported that the precise mechanism by which corticosteroids increase strength in DMD is not known." (PMID 37938624, 2023).
eccrine carcinoma (3 papers, 2012 to 2025). An adenocarcinoma with eccrine differentiation arising from the sweat glands. "A number of other reports have indicated that staining for CD15 and lysozyme may help distinguish between PASGC and eccrine carcinoma and that androgen receptor positivity is strongly associated with PASGC carcinoma." (PMID 25888740, 2015). "Emerging markers such as podoplanin (D2-40) and androgen receptor (AR) have been explored in distinguishing eccrine carcinoma subtypes, though their utility in SEDC remains unclear." (PMID 40282903, 2025).
endocrine cancer (3 papers, 2016 to 2018). "Changes in the length of the CAG polymorphic trinucleotide repeat in the AR gene may lead to the altered transactivation of the AR gene and have been implicated to play a role in the pathogenesis of several forms of endocrine cancer and certain reproductive disorders." (PMID 26885616, 2016). "RAAR was established by CaP researchers seeking to understand better and target more efficiently AR action in this endocrine cancer." (PMID 26876983, 2016). "Components of this network may not only underlie AR‐V7 oncogenicity but possess the dual feature of enhancing AR activity, since positive feedback loops are common in endocrine cancers (including PC)." (PMID 30108134, 2018).
epithelial ovarian tumors (3 papers, 2020 to 2022). "The presence of STS and AR in epithelial ovarian tumors and their association to the overall survival of patients was evaluated using Kaplan–Meier and Cox regression analyses." (PMID 34321053, 2021). "The presence of AR together with MMP-2 in the tumor cells is a risk factor to be considered in epithelial ovarian tumors." (PMID 32718331, 2020). "The present retrospective study demonstrates that the simultaneous expression of STS and AR in epithelial ovarian tumors reduced overall survival of the patients." (PMID 34321053, 2021). "Moreover, the simultaneous expression of STS and AR constitutes an independent predictor of poor prognosis in epithelial ovarian tumors." (PMID 34321053, 2021).
gastric tumor (3 papers, 2012 to 2025). "In the present study, the expression profile of four sex hormone receptors, ERα, ERβ, PR, and AR, was determined in gastric tumors and corresponding normal tissues from a large Chinese cohort, and their clinicopathological and prognostic value was assessed." (PMID 23199240, 2012). "Real-time quantitative PCR showed that the mRNAs of ERα, ERβ, PR and AR were all detected in all 60 pairs of gastric tumors and their matched normal mucosa." (PMID 23199240, 2012). "Our results confirmed the presence of ERα, ERβ, PR, and AR in both gastric tumors and normal mucosa but their expression levels were extremely low except for the predominance of ERβ." (PMID 23199240, 2012). "In the present study, our results show a positive rate of 30.5% in normal mucosa and 23.3% in gastric tumors for PR, and 52.7% in normal tissues and 33.0% in tumors for AR." (PMID 23199240, 2012). "The presence of ERα, ERβ, PR, and AR in both gastric tumors and normal tissues was confirmed but their expression levels were extremely low except for the predominance of ERβ." (PMID 23199240, 2012). "After exclusion of inevaluable cases due to tissue loss or inadequate tissue, the positive rates of ERα, ERβ, PR and AR expression in normal tissues were 38.3%, 97.3%, 30.5%, and 52.7%, and the positive rates of the four receptors in gastric tumor were 12.0%, 91.9%, 23.3%, and 33.0%, respectively." (PMID 23199240, 2012).
hepatitis B (3 papers, 2013 to 2020). "A previous study found that ARs are able to adjust hepatitis B virus transcription and promote the formation of HCC associated with hepatitis B; however, the mechanism by which androgens and the androgen-AR signaling pathway regulate and control hepatocarcinogenesis and its progress are unclear." (PMID 25667651, 2015). "Our study emphasizes the importance of androgen/AR action in the pathogenesis of severe hepatitis B." (PMID 24391916, 2013). "There was a serum testosterone fluctuation during hepatitis B flare and HBV-related ALF, and the median CAG repeats in AR gene exon 1 were associated with lower serum testosterone levels in asymptomatic HBV carriers and an increased susceptibility to HBV-related ALF." (PMID 24391916, 2013). "As the androgen/AR pathway seems to be important for the pathogenesis of hepatitis B, we propose that androgen/AR pathways may potentially impact the onset of HBV-related ALF." (PMID 24391916, 2013). "We demonstrated that there was a serum testosterone fluctuation during hepatitis B flare and HBV-related ALF, and the median CAG repeats in AR gene exon 1 were associated with lower serum testosterone levels in asymptomatic HBV carriers and an increased susceptibility to HBV-related ALF." (PMID 24391916, 2013).
Hyperkalemia (3 papers, 2022 to 2024). An abnormally increased potassium concentration in the blood. "Noteworthy, Spi is a potent FDA-approved MR antagonist, however, less selective because it causes anti-androgenic (via AR) and progestogenic (via progesterone receptor, PR) side effects as well as hyperkalemia." (PMID 37578563, 2023). "On the opposite side, criteria B11 (ACE inhibitors or AR blockers in patients with hyperkalemia), B8 (thiazide diuretics with current significant hypokalemia, hyponatremia, hypercalcemia or gout history) and A1 restricted to hypolipidemic drugs reached more than 90% of reduction." (PMID 38978009, 2024).
hyperuricemia (3 papers, 2020 to 2021). An abnormally high level of uric acid. "The core targets of Plantaginis Herba for the treatment of hyperuricemia were AKT1, mitogen-activated protein kinase 3 (MAPK3), MAPK1, tumor necrosis factor (TNF), prostaglandin-endoperoxide synthase 2 (PTGS2), sirtuin 1 (SIRT1), estrogen receptor 1 (ESR1), and androgen receptor (AR)." (PMID 33897800, 2021).